NUS1 (NUS1 dehydrodolichyl diphosphate synthase subunit)
Diseases named in the same sentence as NUS1 in open-access papers:
NUS1 is named in the same sentence as 76 diseases in open-access papers, as found by Europe PMC text mining. Sharing a sentence is not in itself a finding about the gene and the disease. The quoted sentences say what the papers report.
breast carcinoma (10 papers, 2013 to 2022). "In addition, there is growing evidence that NUS1 is upregulated in several cancer types, such as breast cancer 38, liver cancer 39, 40, and lung cancer." (PMID 35371326, 2022).
epilepsy (9 papers, 2019 to 2025). A brain disorder characterized by episodes of abnormally increased neuronal discharge resulting in transient episodes of sensory or motor neurological dysfunction, or psychic dysfunction. "The clinical presentation of our patient, who began experiencing absence seizures at age 13, aligns with the broad phenotypic spectrum of epilepsy previously reported in association with NUS1 variants." (PMID 41480149, 2025). "Mutations in DHDDS and the gene encoding NgBR (NUS1) are associated with neurodevelopmental disorders that clinically present with epilepsy, motor impairments, and developmental delay." (PMID 40003936, 2025). "Variants in the NUS1 gene are associated with type 2 diabetes, epilepsy and intellectual disability." (PMID 38383672, 2024). "Our findings strongly suggest that this novel variant of NUS1 is responsible for the development of neurological disorders, including epilepsy." (PMID 37470039, 2023). "It is worth noting that 83.33% of the cases were diagnosed with epilepsy-related diseases, indicating a relatively strong causal relationship between NUS1 variants and epilepsy." (PMID 37470039, 2023). "Epilepsy is a common clinical feature among individuals carrying NUS1 variants." (PMID 41480149, 2025). "NUS1 is a relevant gene in multiple diseases, such as epilepsy and congenital glycosylation disorder, and its variants may cause a range of disease manifestations." (PMID 37470039, 2023). "The variability in age of onset and seizure type highlights the heterogeneous nature of epilepsy in the context of NUS1-related neurodevelopmental disorders." (PMID 41480149, 2025). "In two siblings diagnosed with NUS1-CDG, alongside severe neurological impairment, epilepsy, and hearing deficit, these children had visual impairment with discrete bilateral macular lesions at the age of 4 years." (PMID 34925443, 2021).
Parkinson disease (9 papers, 2019 to 2025). A progressive degenerative disorder of the central nervous system characterized by loss of dopamine producing neurons in the substantia nigra and the presence of Lewy bodies in the substantia nigra and locus coeruleus. "Nuclear undecaprenyl pyrophosphate synthase 1 (NUS1) has been implicated in the pathogenesis of neurodevelopmental disorders, including Parkinson's disease, seizures, intellectual disability, dystonia, and congenital disorder of glycosylation." (PMID 40438786, 2025). "The study aimed to investigate the role of NUS1 variants in Parkinson's disease (PD) progression and evaluate plasma Nogo‐B receptor (NgBR) as a potential biomarker." (PMID 40726114, 2025). "Patients with NUS1 variants typically exhibit multiple clinical phenotypes, including Parkinson's disease, congenital disorder of glycosylation, MRD55, and others." (PMID 40438786, 2025). "To date, 25 disease-causing mutations of NUS1 have been reported, which are responsible for various diseases, including dystonia, Parkinson's disease, developmental and epileptic encephalopathy as well as congenital disorder of glycosylation." (PMID 34532305, 2021). "To date, four de novo NUS1 variants have been reported in association with developmental and epileptic encephalopathy (DEE) and early-onset Parkinson’s disease, and one homozygous NUS1 variant has been associated with a congenital disorder of glycosylation." (PMID 31656175, 2019). "To date, only four de novo variants and one homozygous variant have been reported in NUS1, which cause developmental and epileptic encephalopathy, early onset Parkinson’s disease, and a congenital disorder of glycosylation." (PMID 31656175, 2019). "She does not exhibit other neurological symptoms that are also described in NUS1-related disorders, such as parkinsonism or dystonia." (PMID 41480149, 2025).
Dystonia (6 papers, 2021 to 2025). An abnormally increased muscular tone that causes fixed abnormal postures. "Intragenic deletions and duplications can be found in the EPM2A and NHLRC1 (EPM2) genes, ASAH1 gene (SMA-PME), NUS1, and SGCE (myoclonus-dystonia)." (PMID 40584247, 2025).
Ataxia (5 papers, 2019 to 2025). Ataxia refers to impaired coordination of voluntary muscle movement. "Cerebellar ataxia is a commonly reported feature in NUS1-associated disease, frequently accompanied by dysarthria, whereas gait impairment is generally milder in comparison." (PMID 41480149, 2025). "Our study strongly supports the finding that this recurrent, de novo, variant in NUS1 causes developmental and epileptic encephalopathy with involuntary movement, ataxia and scoliosis." (PMID 31656175, 2019). "Here, we report two unrelated Japanese patients with a novel, recurrent, de novo NUS1 variant, who presented with epileptic seizures with involuntary movement, ataxia, intellectual disability and scoliosis." (PMID 31656175, 2019). "The aim of this study is to describe a 41-year-old woman carrying a novel heterozygous NUS1 likely pathogenic variant who presented with PME, as she exhibited myoclonus, tremors, ataxia, and psychiatric symptoms." (PMID 41480149, 2025). "NUS1 should be included in the genetic screening of undiagnosed forms of myoclonus, myoclonus-ataxia, and progressive myoclonus epilepsies." (PMID 35949226, 2022).
developmental delay (5 papers, 2024 to 2025). "In the current study, we described the genetic diagnosis of a rare de novo heterozygous frameshift pathogenic variant in NUS1 in a boy with developmental delay, intellectual disability, and ASD." (PMID 40438786, 2025). "This study enlarges the mutation spectrum of NUS1 and further demonstrates that the mutation of NUS1 may cause developmental delay and ASD." (PMID 40438786, 2025). "In addition, according to previous studies combined with this study, we found 41 NUS1 variants associated with developmental delay and intellectual disability, including 23 missense variants, 5 nonsense variants, 7 frameshift insertion variants, 5 splicing site mutations, and 1 exon deletion." (PMID 40438786, 2025).
Intellectual disability (5 papers, 2021 to 2025). "Clinical presentations of NUS1 gene mutations typically include seizures, intellectual disability, delayed speech, and delayed movement." (PMID 40438786, 2025). "In this study, a novel, de novo pathogenic variant of NUS1 (c.51_54delTCTG, p.L18Tfs*31) was identified in a Chinese patient with intellectual disability and epileptic seizures." (PMID 34532305, 2021).
developmental and epileptic encephalopathy (4 papers, 2019 to 2023). An epilepsy associated with developmental impairment that may be due to either the underlying etiology or the superimposed epileptic activity, or both. "Over 25 variants in NUS1 have been reported, and these variants have been found to be associated with various phenotypes, such as congenital disorders of glycosylation (CDG) and developmental and epileptic encephalopathy (DEE)." (PMID 37470039, 2023).
Myoclonus (4 papers, 2019 to 2025). Very brief, involuntary random muscular contractions occurring at rest, in response to sensory stimuli, or accompanying voluntary movements. "Heterozygous, pathogenic variants of NUS1 have been reported in the cases of early onset syndromes characterized by various combinations of myoclonus, ataxia, intellectual disability, with or without epilepsy." (PMID 40584247, 2025).
congenital glycosylation disorder (3 papers, 2019 to 2023). "Previously, a genetic mutation in NUS1 has been identified in a family with a congenital glycosylation disorder." (PMID 37470039, 2023).
scoliosis (3 papers, 2019 to 2025). A congenital or acquired spinal deformity characterized by lateral curvature of the spine. "Hence, this study strongly suggests that loss-of-function variants in NUS1 that result in loss of the cis-PTase domain in the C-terminus of NgBR may be related to scoliosis and represent a new phenotype." (PMID 33921670, 2021). "Our patient had dyslipemia beginning in her early twenties but did not exhibit dysmorphic features or other manifestations described in some NUS1-related cases, such as scoliosis." (PMID 41480149, 2025). "In contrast with other reported mutations in NUS1 associated with developmental delays, ataxia, intellectual disability, and DEE, both individuals had scoliosis." (PMID 33921670, 2021).
cervical cancer (2 papers, 2017 to 2022). A primary or metastatic malignant neoplasm involving the cervix. "NUS1 down regulates epithelial markers such as E-cadherin and increases mesenchymal markers contributing to EMT in cervical cancer promoting invasion and metastasis." (PMID 35058523, 2022).
diabetes (2 papers, 2019 to 2021). "Our findings from association analysis of diabetes-related biomedical indexes indicated that although NUS1 and GP2 both contribute to the risk of GDM, they might be involved in different mechanisms of GDM." (PMID 34326813, 2021).
type 2 diabetes (2 papers, 2023 to 2024). "Our analysis results suggest an opposing direction of causal effect of NUS1 expression on type 2 diabetes and schizophrenia risk." (PMID 38383672, 2024). "The variants in the 95% credible set from the colocalization are associated with increased expression of NUS1 in these tissues, increased risk of schizophrenia and decreased risk of type 2 diabetes." (PMID 38383672, 2024). "Additionally, type 2 diabetes and schizophrenia colocalize with genetic variants associated with the expression of NUS1 in the cerebellum (PP4 = 0.94), cortex (PP4 = 0.89) and pancreatic islets (PP4 = 0.96)." (PMID 38383672, 2024). "NUS1 has not been previously defined as a putative effector gene for type 2 diabetes nor schizophrenia and is not a target of any approved drug." (PMID 38383672, 2024). "Of these, we defined 15 genes showing evidence of involvement in both type 2 diabetes and schizophrenia with a total score of at least three, and three putative effector genes that displayed at least four different lines of evidence, namely EGR2, LAMA4 and NUS1." (PMID 38383672, 2024). "The biological function of the putative effector genes NUS1 and LAMA4 as well as the result of the enrichment analysis highlight adipogenesis and cholesterol trafficking as potential biological mechanisms influencing the comorbidity between type 2 diabetes and schizophrenia." (PMID 38383672, 2024).
Anxiety (1 paper, 2025). Intense feelings of nervousness, tension, or panic often arise in response to interpersonal stresses. "Additional psychiatric manifestations such as irritability or anxiety have also been described in individuals with NUS1 variants suggesting that certain genetic variants in NUS1 may contribute to an increased susceptibility to psychotic symptoms." (PMID 41480149, 2025).
cognitive decline (1 paper, 2025). "This gradual cognitive decline, beginning in childhood, aligns with previously reported cases of NUS1-related disorders." (PMID 41480149, 2025).
COVID-19 (1 paper, 2022). A disease caused by infection with severe acute respiratory syndrome coronavirus 2. "Based on a threshold of conjFDR <0.05, we identified two loci shared between COVID-19 and T2D: ABO (rs505922, intronic) and NUS1 (rs3924604, intronic)." (PMID 36482905, 2022). "In conclusion, our study has demonstrated genetic pleiotropy between T2D and COVID-19 and has identified shared genetic loci (ABO and NUS1) which were validated with a pathway-based analysis." (PMID 36482905, 2022).
Gestational Diabetes Mellitus (1 paper, 2021). "Given the sharing of pathogenic contribution from genetic factors between T2D and gestational diabetes mellitus (GDM), we conducted the study to systematically examine the relationship of NUS1 and GP2 genes with the susceptibility to GDM in Chinese Han population." (PMID 34326813, 2021).
Hepatic steatosis (1 paper, 2023). Steatosis is a term used to denote lipid accumulation within hepatocytes. "Importantly in the context of systemic glucose homoeostasis, Nogo-B interacts with the Nogo-B receptor (NgBR, encoded by NUS1) and knockout of Nus1 in mice causes hepatic steatosis, possibly be interfering with insulin signalling." (PMID 37137910, 2023).
kidney cancer (1 paper, 2022). Primary or metastatic malignant neoplasm involving the kidney. "But the relationship between NUS1 and kidney cancer has not been fully elucidated." (PMID 35371326, 2022).
Lafora disease (1 paper, 2025). Lafora disease (LD) is a rare, inherited, severe, progressive myoclonic epilepsy characterized by myoclonus and/or generalized seizures, visual hallucinations (partial occipital seizures), and progressive neurological decline. "Although this condition is pathophysiologically distinct from NUS1-related disorders, metformin has demonstrated broader neuroprotective effects that extend beyond its use in Lafora disease." (PMID 41480149, 2025).
psychosis (1 paper, 2025). "While lurasidone has demonstrated efficacy in treating psychosis through its D2 and serotonergic antagonism, we hypothesized that metformin might contribute through mechanisms related to mitochondrial dysfunction associated with NUS1 variants." (PMID 41480149, 2025).
renal carcinoma (1 paper, 2022). A carcinoma arising from the epithelium of the renal parenchyma or the renal pelvis. "In this study, we firstly detected that miR-184-5p regulates the proliferation and migration of renal cancer cells by directly targeting NUS1." (PMID 35371326, 2022).
schizophrenia (1 paper, 2024). A major psychotic disorder characterized by abnormalities in the perception or expression of reality. "Differential expression analysis in brain supports this evidence, as NUS1 is over-expressed in schizophrenia patients." (PMID 38383672, 2024).
cancer (7 papers, 2013 to 2025). A tumor composed of atypical neoplastic, often pleomorphic cells that invade other tissues. "NUS1 and RCN1 were selected based on their significantly higher expression in OSCC tissues (more than twofold compared to adjacent non-cancerous tissue), supported by previous reports of their roles in other cancers." (PMID 40869423, 2025).
neurodevelopmental disorder (5 papers, 2020 to 2025). A behavioral and cognitive disorder with onset during the developmental period that involves impaired or aberrant development of intellectual, motor, or social functions. "Interestingly, recent studies found that mutations in NUS1 cause not only neurodevelopmental disorders but also neurodegenerative disease." (PMID 32542927, 2020).
movement disorder (2 papers, 2025). Neurological conditions resulting in abnormal voluntary or involuntary movement, which may impact the speed, fluency, quality and ease of movement. "Movement disorders are present in most individuals with NUS1 variants and typically manifest during early childhood." (PMID 41480149, 2025). "The molecular mechanisms underlying NUS1-associated movement disorders remain largely unexplored." (PMID 40438786, 2025). "A recent study demonstrated that patients with NUS1 variants display movement disorder phenotypes similar to those with DHDDS mutations, prompting the recommendation for NUS1 gene inclusion in movement disorder diagnostic screening panels." (PMID 40438786, 2025).
NUS1 also shares sentences with these, for which no sentence is quoted: tumor (9 papers); breast tumor (6); lung carcinoma (5); invasive ductal breast carcinoma (4); hepatocellular carcinoma (3); liver cancer (3); melanoma (3); Seizure (3); autism spectrum disorder (2); cerebellar ataxia (2); cerebral cavernous malformation (2); clear cell renal cell carcinoma (2); liver fibrosis (2); lysosomal storage disorder (2); neurological diseases (2); non-small cell lung carcinoma (2); Progressive myoclonic epilepsy (2); Tremor (2); absence seizures (1); attention deficit-hyperactivity disorder (1); Auditory hallucination (1); autosomal dominant mental retardation-55 (1); autosomal recessive disease (1); autosomal recessive retinitis pigmentosa (1); cholestasis (1); Cirrhosis (1); Cognitive impairment (1); congenital sensorineural deafness (1); diabetic kidney disease (1); Ductal Carcinoma (1).
A further 19 diseases each share a sentence with NUS1 in 1 paper.